GDF15 (growth differentiation factor 15)
Diseases named in the same sentence as GDF15 in open-access papers (continued):
Sharing a sentence is not in itself a finding about the gene and the disease.
Obesity (continued). "GDF15 serum levels have a strong association with many diseases, including inflammation, cancer, cardiovascular diseases, and obesity, and potentially serve as reliable predictor of disease progression." (PMID 30542297, 2018). "Numerous age-related conditions (atherosclerosis, chronic kidney disease, obesity and diabetes, cancer and cognitive impairment) are also associated with elevated GDF-15, making it a clinically relevant biomarker." (PMID 27734214, 2017). "GDF15 was previously shown to mediate adult body weight loss in cachexia and obesity settings, through its action in the hypothalamus (reducing Npy and increasing Pomc expression) that regulates food intake." (PMID 28572090, 2017). "Increased GDF-15 levels are associated with cardiovascular diseases such as hypertrophy, heart failure, atherosclerosis, endothelial dysfunction, obesity, insulin resistance, diabetes, and chronic kidney diseases in diabetes." (PMID 26273671, 2015). "These processes are more common at higher age, male sex, smoking, obesity, and diabetes mellitus, contributing to the association between GDF-15 level and cardiovascular and cancer diseases." (PMID 24312445, 2013). "Although further studies are necessary to discern between these possibilities, this potential association of GDF15 with the improvement of obesity and T2D might be related to its role in metabolic homeostasis by suppressing food intake, favouring weight loss." (PMID 40377893, 2025). "The individual loss of endogenous Gdf15 or Fgf21 has been studied in the context of obesity." (PMID 40787810, 2025). "The study predicts that this long-acting GDF15 analog could achieve double-digit percentage weight loss in human obesity treatment." (PMID 40837873, 2025). "Notably, our research demonstrates that elevated GDF-15 levels are closely associated with an increased risk of metabolic complications and heightened inflammation in individuals affected by both obesity and diabetes." (PMID 40722664, 2025). "Additionally, GDF15 showed a strong correlation (p < 0.05) with both TGs (r = 0.314) and BMI (r = 0.239), indicating a close association between GDF15 and obesity." (PMID 41497484, 2025). "Nonsteroidal anti-inflammatory drug-activated gene (NAG-1), also known as growth differentiation factor 15 (GDF15), is a member of the transforming growth factor-β superfamily and has been associated with anti-obesity properties and preservation of kidney function." (PMID 40399974, 2025). "Alternatively, obesity‐associated human‐specific changes in GDF15/GFRAL/RET complex signalling could be present, reducing its efficacy." (PMID 39907315, 2025). "Firstly, the stress caused by RYGB surgery may lead to an increase in GDF15 levels, which could facilitate the early resolution of T2D and the improvement of obesity alterations following bariatric surgery, then returning to presurgical levels." (PMID 40377893, 2025). "Third, in terms of obesity, it was reported that GDF15 might be affected by body weight and associated with body mass index disproportionally." (PMID 40142684, 2025). "Conversely, downregulation of GDF15 is implicated in promoting the development of obesity." (PMID 39700016, 2024). "Furthermore, the endogenous upregulation of GDF-15 is associated with resistance to diet-induced obesity, improved glucose homeostasis, and increased insulin sensitivity." (PMID 38791028, 2024). "However, the anorexic nature of GDF15 and its association with cancer cachexia and chemotherapy-induced anorexia have hampered its therapeutic potential in the treatment of obesity." (PMID 38310105, 2024). "Notably, alteration in ciliary function and modulation of ADCY3 and GDF15 have all been linked to the regulation of energy homeostasis, food intake, and obesity." (PMID 38719753, 2024). "However, being ubiquitously expressed, GDF15 has been associated with a range of diseases such as cancer and pathologies of the liver, kidney and cardiovascular system, as well as obesity." (PMID 38719753, 2024).
Obesity (continued). "Conversely, increasing GDF15 levels by transgenic overexpression or pharmacological administration of recombinant GDF15 induces weight loss and improves cardiometabolic parameters in mice with diet-induced obesity and macaques with spontaneous obesity." (PMID 38310105, 2024). "Both FGF21 and GDF15 have been shown to modulate energy balance and glucose homeostasis, and their pharmacological administration leads to promising beneficial effects against obesity and associated metabolic diseases in pre-clinical models." (PMID 37818094, 2023). "Obesity is also associated with increased serum concentrations of GDF15." (PMID 37818094, 2023). "Furthermore, a multiple linear regression analysis suggests that the reduction in GDF-15 at 1 year from baseline was associated with a greater PWL after anti-obesity treatments." (PMID 37436597, 2023). "Interestingly, higher levels of GDF15 have been associated with a higher prevalence of NAFLD in youth with obesity, as well as in overweight adults, with higher levels of circulating GDF15 linked to worsening of liver fibrosis." (PMID 37686725, 2023). "Additionally, GDF15 is secreted in adipose tissue macrophages of mice to combat the inflammatory effects of obesity-associated lysosomal stress, and prevents insulin resistance." (PMID 37538245, 2023). "GDF-15 has been shown to be a stress responsive cytokine associated with obesity and diabetes." (PMID 37283763, 2023). "In addition, GDF15 increases lipolysis, thermogenesis, and metabolism of oxidative metabolites, thereby reducing the risk of developing obesity, IR, and related oxidative complications." (PMID 36444166, 2022). "Moreover, in one study, an engineered long-acting recombinant GDF15 protein was shown to exert a strong weight-lowering effect in obese mice and monkeys, confirming its potential application for treating obesity and associated metabolic disorders." (PMID 35909571, 2022). "Together, our results demonstrate that CPT ameliorates obesity and associated metabolic abnormalities in mice, which may be due to elevations of circulating GDF15." (PMID 35202387, 2022). "Furthermore, related studies have identified obesity, diabetes, hypertension, serum sST2 levels, and GDF-15 levels as significant factors affecting the increased risk of CAD." (PMID 36337880, 2022). "Similarly, genetic overexpression of Gdf15 results in decreased body weight and increased resistance to obesity associated with high-fat diets, whereas Gdf15 and Gfral deficient mice are more susceptible to diet-induced obesity." (PMID 35916366, 2022). "As preclinical data in mice strongly implicated Gdf15 in the aetiology of obesity and glucose tolerance, we specifically investigated whether human genetic evidence supports these findings." (PMID 35916366, 2022). "It is hypothesised that this contradictory finding of upregulated levels in obesity but weight loss upon overexpression may be explained by GDF15 acting as a signal to the brain to induce weight loss." (PMID 35916366, 2022). "GDF15 is also induced by mitochondrial stress, and is associated with various diseases such as inflammation, cancer, cardiovascular disease, mitochondrial disorders, chronic liver disease, and obesity." (PMID 36046792, 2022). "We hypothesized that GDF-15 would be associated with components of the immune system in children with obesity." (PMID 34521901, 2021). "Gdf15 impairs progression of non-alcoholic fatty liver disease in obese mice by enhancing fatty acids oxidation and its deficiency promotes high fat diet-induced obesity and exacerbates liver injury induced by chronic alcohol and carbon tetrachloride exposure." (PMID 33761883, 2021). "The positive association between GDF-15 level and obesity progression may therefore result from the pro-inflammatory status of SFA-activated macrophages, given that pro-inflammatory macrophages are involved in the development of obesity complications." (PMID 33302552, 2020).
Obesity (continued). "Food intake drives obesity in strains deficient for melanocortin 2 receptor accessory protein 2, Mrap2-/-, carboxypeptidase E, Cpe-/-, proprotein convertase 1, Pcsk1+/-, or growth differentiation factor 15, Gdf15-/-." (PMID 32356724, 2020). "Considering that obesity is an important factor associated with circulating GDF15 levels, we also analysed whether the relationship between serum GDF15 levels and LEAD was affected by body mass index (BMI)." (PMID 32222153, 2020). "On the contrary, Gdf15-deficient mice are prone to obesity and IR." (PMID 33302552, 2020). "Moreover, higher FGF21 and GDF15 circulating levels are associated with age-related diseases such as obesity, cardiovascular disease, insulin resistance, type 2 diabetes, and neurodegeneration, as well as cancer cachexia." (PMID 33374852, 2020). "Notably, mice with GDF15 deletion are susceptible to diet-induced obesity compared to controls, indicating the possible protective role of GDF15 against the severity of diet-induced obesity." (PMID 32671100, 2020). "Considering that obesity is an important factor associated with circulating GDF15 levels, whether the relationship between serum GDF15 levels and LEAD is affected by body mass index (BMI) was also analysed." (PMID 32222153, 2020). "Moreover, GDF15 is implicated in aging and in the development of aging-related pathological diseases such as obesity, cardiovascular diseases, diabetes or cancer." (PMID 29717162, 2018). "Gene expression studies on hNAG-18 have shown that GDF-15 may influence age-associated pathology development through mechanisms related to obesity, appetite, insulin sensitivity, energy metabolism and mTOR activity." (PMID 27734214, 2017). "Scientific data showed that serum GDF-15 could be a potential marker to identify individuals who are at risk for diabetes and obesity." (PMID 26273671, 2015). "Finally, few studies differentiated between heart failure phenotypes when evaluating GDF-15’s involvement, particularly in patients with obesity, where it may have greater diagnostic and prognostic significance." (PMID 41597417, 2026). "Thus, GDF15 might be able to restore impaired sympathetic innervation or activity associated with obesity, high-fat diet, diabetes or aging, which might help improve the metabolic profile or ameliorate age-related pathology." (PMID 41034527, 2025). "GDF-15 may play a role in the metabolic dysregulation associated with obesity." (PMID 37645520, 2023). "In addition to the anti-obesity property of CPT-induced GDF15 elevation, GDF15 is also implicated in life span, atherosclerotic cardiovascular disease, inflammation and immunology, mitochondrial disease, cancer, rheumatoid arthritis, chronic renal, and cardiac failure." (PMID 35202387, 2022). "In the current study, we explored the association of circulating plasma concentrations of GDF15 with NAFLD in youth with overweight/obesity, and whether changes in plasma concentrations in GDF15 parallel the changes in intrahepatic fat content (HFF%) over time." (PMID 35194014, 2022). "GDF15 is involved in the regulation of appetite and metabolism, showing potential for the treatment of obesity and related comorbidities." (PMID 41915091, 2026). "We recently showed that selective deletion of the mitochondrial fusion protein optic atrophy 1 (OPA1) in brown adipocytes (OPA1 BKO) leads to GDF15 secretion, partially mediating resistance to diet-induced obesity (DIO), and improving thermoregulation." (PMID 41974995, 2026). "Despite GDF-15 relevance in cardiometabolic disorders, several gaps still remain regarding its implication in the triad of obesity–heart failure–subclinical atherosclerosis." (PMID 41597417, 2026). "Several studies have reported that HFD feeding increases circulating GDF15 in mice, supporting its use as a metabolic stress marker in diet-induced obesity models." (PMID 41596279, 2026).
Obesity (continued). "This review aimed to evaluate the impact of bariatric and metabolic surgery (BMS) in the levels of circulating GDF15 in individuals with obesity." (PMID 41915091, 2026). "Although GDF15 is a promising target for obesity, the function and cellular source of GDF15 during MASLD are not fully understood." (PMID 40494889, 2025). "The aim of the present study was to analyze the association between circulating concentrations of GDF15 and FGF21 in obesity and type 2 diabetes (T2D) in the context of aging." (PMID 40828431, 2025). "Circulating GDF15 levels were measured in normal-weight individuals and patients with obesity before BS and at 3, 6 and 12 months post-surgery." (PMID 40530451, 2025). "Only supraphysiological doses of exogenous GDF15 have demonstrated metabolic improvements in obesity-induced T2D animal models." (PMID 40629349, 2025). "Conversely, maladaptive effects (e.g., low-grade inflammation) were attributed to GDF-15 in chronic conditions (e.g., obesity, aging)." (PMID 40272732, 2025). "Study of GDF15's impact on energy balance and inflammation has led to clinical development of GDF15‐mimetics for obesity and metabolic syndrome and GDF15‐inhibitors or antagonists for cancer‐related cachexia, immunosuppression and heart disease." (PMID 40019842, 2025). "This study is designed to investigate the levels of GDF-15 in individuals afflicted with diabetes, obesity, and insulin resistance." (PMID 40722664, 2025). "A dual GLP-1/GDF15 agonist led to greater reductions in body weight, food intake, insulin, fasting glucose, and triglycerides compared to individual treatments, highlighting GDF15’s potential in obesity management." (PMID 40530451, 2025). "They reported that WAT is the primary source of GDF15 at the onset of obesity and T2D (due to macrophage accumulation), while the liver becomes more involved during progression to MASH, with GDF15 expression rising in hepatocytes as the disease advances." (PMID 40530451, 2025). "Much of the GDF15 obesity and exercise data comes from adult or animal literature, describing GDF15 correlations with bouts of exercise, lower BMIs and decreased appetite." (PMID 40019842, 2025). "Its association with obesity, insulin resistance, and T2DM is well-established, with GDF-15 levels positively correlated with impaired fasting glucose (IFG) and newly diagnosed diabetes (NDD)." (PMID 41019919, 2025). "These observed positive correlations between the GDF-15 levels and obesity/diabetes markers appear to be a compensatory response to the underlying pathological effects of the metabolic disruptions observed in obese and diabetic patients." (PMID 40722664, 2025). "Growth differentiation factor 15 (GDF-15) is a potential therapeutic target for obesity due to its role in appetite suppression." (PMID 39902404, 2025). "Metabolic stress induced by obesity triggers GDF15 secretion from hepatic and adipose sources, leading to increased circulating levels." (PMID 40837873, 2025). "Obesity, insulin resistance, and inflammatory cascades enhance the transcription of GDF-15 through SMAD-signaling pathways, thereby mitigating the elevation of blood pressure induced by metabolic stress." (PMID 40371061, 2025). "Taken together, obesity, presence of type 2 diabetes, serum glucose concentrations, and HbA1c levels are correlated with higher GDF15 concentrations in serum and CSF." (PMID 40820083, 2025). "Two primary strategies include GDF15 analogues as GFRAL agonists for obesity treatment and GDF15‐derived peptides as antagonists to counteract cancer‐induced cachexia and related disorders." (PMID 39907315, 2025). "The discovery of the role of GDF15 in the anti-obesity effects of metformin offers new possibilities for targeted therapies to address the global obesity epidemic." (PMID 40837873, 2025). "Growth differentiation factor 15 (GDF-15) is a cytokine with an emerging interest in obesity and MASLD." (PMID 40794228, 2025).
Obesity (continued). "Consistent with previous findings, our study not only confirm the critical role of GDF15 in weight regulation, but also provides a clinically feasible long-term dietary intervention strategy for obesity management." (PMID 41204286, 2025). "GDF15 is also secreted in other conditions, including exercise, obesity, and aging, and acts centrally to suppress appetite and regulate energy balance." (PMID 40403112, 2025). "Regarding its precise anorectic and immune checkpoint functions, anti-obesity drugs have been developed by exploiting its activating effects, such as GDF15 analogs and GFRAL receptor agonists." (PMID 40837873, 2025). "Further studies would be necessary to understand the implications of the changes in FGF21 and GDF15 after bariatric surgery, which follow a different pattern, in relation to the improvement of obesity and the resolution of T2D." (PMID 40377893, 2025). "GDF15 analogs are under clinical evaluation for cardiometabolic diseases and obesity, whereas monoclonal antibodies have been tested in cancer-associated cachexia." (PMID 40174478, 2025). "Plasma GDF15 levels increased significantly after bariatric surgery in patients with obesity and normoglycemia (p < 0.01), as well as in those with obesity and impaired glucose tolerance or T2D (p < 0.05)." (PMID 40377893, 2025). "In summary, our study provides a comprehensive examination of the correlation between circulating GDF-15 levels and multiple factors, including age, gender, race, diabetes, and obesity." (PMID 40722664, 2025). "Patients with obesity were evaluated before and 3, 6, and 12 months after BS, and circulating GDF15 levels were analysed in relation to clinical, biochemical, and anthropometric parameters." (PMID 40530451, 2025). "This study aimed to evaluate the changes in circulating GDF15 levels in obesity, to assess their correlations with anthropometric, clinical, and biochemical parameters, and to determinate the impact of BS on these values and associated correlations." (PMID 40530451, 2025). "Fasting circulating levels of GDF15 were measured in patients with obesity (obese group) both before and at 3, 6, and 12 months after BS." (PMID 40530451, 2025). "Given the rapid increase in obesity prevalence, newer medications have been proposed, with recent studies highlighting the role of growth/differentiation factor 15 (GDF15)." (PMID 40724891, 2025). "This pilot study examines the impact of ASBs on the therapeutic effects of metformin in pediatric patients with obesity and prediabetes, focusing on growth differentiation factor 15 (GDF-15) as a potential mediator." (PMID 40077667, 2025). "Circulating GDF15 levels were elevated in patients with obesity compared to normal-weight individuals and were higher in men than in women." (PMID 40530451, 2025). "These plasma cytokine data support a generally heightened basal inflammatory state in obesity coupled with altered GDF-15 and FGF-21 responses to 48 h fasting." (PMID 40662191, 2025). "That said, this was the first study to explore metformin-responsive GDF-15 secretion in a pediatric population with prediabetes and obesity." (PMID 40077667, 2025). "Our study represents a substantial stride in advancing our understanding of the potential significance of GDF-15 in obesity and diabetes, highlighting its promising role as a biomarker for metabolic disease among various ages, genders, and ethnic groups." (PMID 40722664, 2025). "Currently, pharmaceutical companies worldwide have embarked on drug research with GDF15 as a novel therapeutic target, encompassing various fields such as obesity, cancer, and anorexia syndrome." (PMID 40837873, 2025). "Current evidence indicates that the anti-obesity effects of the classic KD are primarily mediated through two distinct pathways: GDF15-induced appetite suppression (reducing energy intake) and FGF21-enhanced energy expenditure (increasing metabolic activity)." (PMID 41204286, 2025).